CD44 (CD44 molecule (IN blood group))
Diseases named in the same sentence as CD44 in open-access papers (continued):
Sharing a sentence is not in itself a finding about the gene and the disease.
tumor (continued). "Although our data indicates that CD44 does not preferentially select for tissue-specific metastasis in vivo, CD44 knockdown on stem-cell-like CD44+/CD24−/low MDA-MB-231 cells did significantly decrease tumor burden and reduced the incidence of metastatic lesions in the hind limbs of animals." (PMID 25888636, 2015). "Long-term activation of CD44 has been reported to play a key role in tumor progression." (PMID 26530123, 2015). "Following a first line therapy, at the time at which PDAC became resistant, CD44+ cells not only persist in the recurrent tumor but they acquire the capacity to proliferate, suggesting an important role in tumor recurrence and thus in the particularly bad prognosis." (PMID 26244163, 2015). "More preclinical studies are now needed to confirm these results and to evaluate the toxicity of this therapeutic approach, and in parallel, to study the signaling pathway controlled by CD44 during tumor recurrence with a view to developing specific inhibitors." (PMID 26244163, 2015). "It is likely that HA distinguishes activated CD44 on tumor cells from normal cells, and the use of HA as a selective targeting carrier might serve as a promising avenue for systemic anti-cancer therapeutics." (PMID 25909172, 2015). "It was found that the all mice immunized with the CD117+CD44+CSC vaccine grew tumors in 22 days but the tumor volume was statistically significant decreased compared with the mice immunized with the SKOV3 cell vaccine (*p < 0.05) or the non-CD117+ CD44+CSC vaccine (**p < 0.01)." (PMID 26497895, 2015). "CD44 was also directly connected with miR-335 and relevant to tumor." (PMID 25874214, 2015). "Ezrin can directly interact with the cytoplasm of CD44 molecules, influence conformation of cytoskeletal protein and its distribution, change apoptosis of tumor cells, regulate cell-cell adhesion with extracellular matrix, and promote metastasis and proliferation of tumors." (PMID 25929323, 2015). "Furthermore, as a subtype of NEPC cells, small cell neuroendocrine carcinoma (SCNC) is often seen in patients with advanced disease, and is composed of pure neuroendocrine (NE) tumor cells that express PCa stem cell marker CD44." (PMID 25797256, 2015). "A strong increase of CD44 was found in the tumor recurrence of mouse model." (PMID 25823654, 2015). "These aptamers bind specifically to CD44-expressing tumor cells with high efficacy." (PMID 25954275, 2015). "Pan-CD44 monoclonal antibodies have been shown to reduce tumor growth, metastasis and post-radiation recurrence of pancreatic xenograft tumors, while have also been reported to drastically decrease the leukemic population in mice transplanted with human acute myeloid leukemic stem cells, as well." (PMID 26569327, 2015). "Tumor cells were predominantly CD44+/CD24- and CD49f+/EpCAM+." (PMID 26311223, 2015). "It was recently reported that oligomeric hyaluronan induce CD44 shedding from tumor cells." (PMID 26347743, 2015). "Although HA is reported to have a rheostatic effect on CD44, with high molecular weight HA inhibiting tumor progression, and low molecular weight HA stimulating tumor progression, the extent to which A6 may differentiate these activities has yet to be studied." (PMID 25870596, 2015). "CD44 expression also correlated with Furhman grade, tumour recurrence and MVI of RCC." (PMID 26287771, 2015). "In addition to its well-known biocompatibility, hyaluronan can act as a suitable carrier being endowed with the capability to selectively target tumor cells through the binding to CD44." (PMID 26097871, 2015). "Because CD44+ stem cells are one of the major stem cells in cancers involved in self-renewal capacity, enhanced tumor initiation, and drug resistance, we decided to examine whether VTD can target these specific populations." (PMID 26188124, 2015). "Tumor cells from miR-146a-deficient mice showed lower expression of memory B-cell/activation related antigen, CD80, but similar expression of CD44." (PMID 25906746, 2015).
tumor (continued). "CD44 participates in the extravasation and migration of tumour cells." (PMID 26287771, 2015). "Do ICAM1 and CD44 share common signaling networks to maintain tumor stemness?" (PMID 26571024, 2015). "Knowing that the CD44+ is a commonly used cancer-stem-cell biomarker, our targeted biotin-MBs could be a potent tool to sort cancer stem cells from dissected tumor tissue for use in preclinical experiments and clinical trials." (PMID 25993512, 2015). "Although its expression has previously been found to correlate with increased tumor malignancy and tumor stemness, CD44 has not been associated with VM before." (PMID 26189059, 2015). "Most commonly these CD44 siRNAs have been delivered to tumor cells using nanoparticles." (PMID 25954275, 2015). "Although EpCAM, CD133, CD24 and CD44 were expressed in all three subpopulations of Li-7 cells in vitro, interestingly, they were expressed only in a very low proportion of tumor cells expressing CD13 in vivo." (PMID 25885470, 2015). "Histopathological analysis of original and mouse xenograft tumors revealed that CSC-like derived tumors closely reproduced the histotype of the original CMC (i.e. carcinoma predominantly organized in tubular structures), including CD44 expression in scattered tumor cells evaluated by IHC." (PMID 25884842, 2015). "Similarly, IHC staining of AF1q or CD44 in human breast normal and tumor specimens showed that AF1q expression areas roughly matched with the CD44 signals." (PMID 26079538, 2015). "By binding to growth factors and presenting them to their receptors, CD44 might be involved in the activation of tumour-promoting signaling pathways." (PMID 25999819, 2015). "The CD44+/CD24− tumor cell phenotype is recognized as a cancer stem cell characteristic." (PMID 25429827, 2015). "In particular, CD44 is the receptor for hyaluronate and osteopontin, critical for cell adhesion and invasion, and is a key marker of reactive astrocytes, whose infiltration in the tumor and in the peritumoral area correlates with a worse prognosis." (PMID 26188123, 2015). "As CD44 is the main receptor for hyaluronan, and the hyaluronan binding domain exists in all CD44 isoforms, much effort has focused in blocking the CD44-HA interaction based on abundant evidence that the CD44-HA interaction is involved in tumor progression." (PMID 26569327, 2015). "To further confirm the effects of Wnt/β-catenin signaling on tumor sphere formation and the CD44+/CD24− BCSC subpopulation using an alternative method of inhibition, we treated 4T1 cells with another well-known small-molecule Wnt/β-catenin signaling inhibitor, FH535." (PMID 26202299, 2015). "Cells that have increased CD44 have been shown to be more aggressive in terms of growth and motility, and could be responsible for increased tumor growth seen in our established model." (PMID 26312209, 2015). "Other studies suggest that these mesenchymal-like cells can recapitulate the epithelial population of a tumor following chemotherapeutic therapy, potentially representing the HNSCC tumor equivalent to the CD44+/CD24− stem-like subpopulation in breast carcinomas." (PMID 25734659, 2015). "Therefore, CD44 expression can be used as a marker to predict post-operative prognosis and tumour progression." (PMID 26287771, 2015). "After sufficient tumor regrowth, we evaluated CD44 expression by immunofluorescence." (PMID 25797268, 2015). "In addition, the cytoplasmic domain of CD44 interacts with merlin to regulate actin organization, cell motility, and tumor suppression." (PMID 26572077, 2015). "Although it is clear that the nanoparticles are taken up by tumor cells or tissues via receptor-medicated endocytosis, it is less clear whether the nanoparticles are taken up only through CD44-medidated endocytosis." (PMID 25954275, 2015). "Furthermore CD44 represents the main receptor of HA whose binding with CD44 promotes signaling pathways that induce tumor growth, survival as well as cancer cell invasion." (PMID 25629807, 2015).
tumor (continued). "Both large HA polymers and their smaller catabolic products selectively activate CD44 isoform-mediated cellular signaling that regulates inflammation, anti-apoptosis, and tumor cell growth, as well as differentiation, DNA repair, and keratinocyte survival function." (PMID 26029210, 2015). "However, CD44+α2β1+ LAPC4 cells displayed (statistically) higher tumor-regenerating activity than the corresponding CD44−α2β1− LAPC4 cells." (PMID 26246472, 2015). "Although CD44 is a marker of leukocytes, histological analysis at higher magnification demonstrated that CD44 was expressed by those tumor cells directly lining the blood lakes, as was similarly described for vascular endothelial (VE)-cadherin, a well-defined marker of VM." (PMID 26189059, 2015). "These cancer stem cells (CSCs) that have the ability to seed a tumor were shown to be CD44+." (PMID 25904917, 2015). "In addition, CD44 is responsible for cell adhesion, cell-cell interaction, lymphocyte activation, and tumor metastasis." (PMID 26056562, 2015). "Moreover, we show that putative cancer stem cell markers including CD133, CD15, A2B5 and CD44 were present on genetically distinct tumour cell populations." (PMID 24154962, 2014). "They display enhanced tumor proliferating and metastatic capacities in CD44+ population." (PMID 24618337, 2014). "Some markers, such as ALDH1, CD133, and CD44, are common across all tumors, while others may be relatively tumor specific, e.g., CD271 in melanoma and Trop2 for prostate." (PMID 25566504, 2014). "CD44 was critical in cell motility, tumor development and invasion." (PMID 25551689, 2014). "First, CD24+/CD44+ cells may have been generated during the in vivo tumor growth from CD24-/CD44+ cell population." (PMID 24612587, 2014). "CD44 caused a rather uniform membrane staining of the tumor cells, which did not reflect the level of tumorigenicity seen in HNSCC xenografts studies." (PMID 24593279, 2014). "Interestingly, in all tested biopsies EGFR+ tumour cells displayed a significantly higher DI than stromal haematopoietic cells (CD45+/CD44+)." (PMID 24154962, 2014). "CD44+/CD24- tumor cells (CSC) from clinical specimens were sorted using flow cytometry." (PMID 24884516, 2014). "Secreted serglycin in the tumor microenvironment may interact with CD44 on tumor cells triggering CD44 signaling." (PMID 24455486, 2014). "CD44 may also inhibit tumor progression by binding to high molecular weight hyaluronan and promote its interaction with hypophosphorylated Merlin, inhibit RAS activation, inhibit CD44–ERM interactions and suppress EGFR activation." (PMID 24760019, 2014). "Moreover, a recent study has indicated that high expression levels of hCSCs biomarkers, including CD133 and CD44, are correlated with tumor angiogenesis and poor prognosis of HCC patients." (PMID 24721996, 2014). "Interestingly, prophylactic celecoxib regimen also suppressed the expression of CD133 and CD44 in tumor tissues." (PMID 24721996, 2014). "Interestingly, the ALDH positive tumor cells exhibited more tumorigenic potential when compared to CD44 positive cells." (PMID 24533098, 2014). "Patients with HPV-positive OPSCC, with biomarkers for good response to therapy e.g., low MHC class I, or CD44 expression or high numbers of CD8+ tumor infiltrating lymphocytes, could be included in randomized trials with less severe therapy." (PMID 24676623, 2014). "Western blotting analysis demonstrated that the downstream targets of β-catenin, including VEGF, c-myc and CD44 were up-regulated in miR-9 overexpressed cells, suggesting that these genes may participate in the tumor metastasis in ESCC." (PMID 25375090, 2014). "Interestingly, CD44 has been reported to be enriched at the cell surface of various types of tumor-initiating cells, which bear similarities with embryonic or adult stem cells and are often referred to as cancer stem cells (CSCs)." (PMID 25364760, 2014).
tumor (continued). "However, well-designed studies are required to determine the role of the signaling pathway of CD44 regulation in tumor aggressiveness and CSCs." (PMID 24699672, 2014). "CD44 has been demonstrated to be critical for keratinocyte, fibroblast, and smooth muscle cell HA coat formation and both CD44 and RHAMM have recently been implicated in the binding of HA to tumor cells and fibroblasts." (PMID 25276814, 2014). "Therapeutic celecoxib can retard tumor growth and inhibit CD44+/CD133+ hCSCs." (PMID 24721996, 2014). "The lower expression of CD44, by using blocking antibodies, proteases or specific ligands, may regulate tumor metastasis." (PMID 24788523, 2014). "All data presented here strongly support our hypothesis that the tumor-suppressive effect of miR-34a is mediated by directly targeting CD44." (PMID 25551284, 2014). "Moreover, CD44+/CD133+ hCSC abundance was increased in regions near COX-2-expressing non-tumor tissues compared with regions that were farther away." (PMID 24721996, 2014). "To determine whether CSCs are linked with tumor aggressiveness or malignancy, we performed flow cytometric analyses of bCSC markers CD44+/CD24-/low in patient-derived tumor samples of different stages." (PMID 25315241, 2014). "Immunohistochemical staining for CD24 and CD44 on tumor tissues isolated from tumor xenografts at the end of the study were performed to determine whether CD24+/CD44+ CSC maintained their phenotype at the end of the experiment." (PMID 24612587, 2014). "In addition, strong positive staining for CD44 was observed not only on the surface of salivary gland appearing structures, but also on the dense carcinoma cells within the tumor mass as well." (PMID 24612587, 2014). "In addition, the transition of tumor and non- tumor tissue of each sample (as control) was examined for the presence of CD44 and CD133." (PMID 25635255, 2014). "Rall, C. J. studied CD44 expression in 21 clinical PCa tissues and reported the expression of CD44v6, CD44v8-9, CD44v8-10 and CD44s, although only CD44v6 may be involved in tumor metastasis." (PMID 24708709, 2014). "However, CD44 is widely expressed in most cells in HNSCC tumor samples and several cell lines tested." (PMID 24612587, 2014). "Our results demonstrate that the heterogeneity of tumor cells has important clinical implications for the treatment of HNSCC and that some of the CD44 variants may be associated with increased radioresistance." (PMID 24122205, 2014). "Following tumor cell disassociation, tumor cell samples were incubated with anti-CD44, anti-CD24, and anti-lineage mixture antibodies (PE-conjugated anti-CD2, CD3, CD10, CD16, CD18, CD31, and CD 140b), and then labeled by Aldefluor assay, and analyzed using MoFlo Astrios flow cytometry." (PMID 26932376, 2014). "Moreover, tumor cells were treated with a blocking anti-CD44 mAb to disclose the relevance of this receptor in the interaction of HA-conjugated drugs with target cells." (PMID 25383653, 2014). "CD44, the hyaluronan receptor, has been identified as another target of AP-1 that mediated cell adhesion required for tumor cell migration as well as growth and dissemination of a variety of tumor types." (PMID 25260594, 2014). "In contrast, immunostaining with polyclonal CD44 (clone F10-44-2; Invitrogen/Biosources, USA) revealed three different patterns of expression in different areas of the same tumor, i.e. clearly membrane, as well as cytoplasmic and clearly nuclear in other parts." (PMID 24921652, 2014). "Given the reported involvement of ezrin and ankyrin in cancer progression and of merlin in tumour suppression, we speculate that the spatial availability of CD44 to interact with specific cytosolic partners may differentially regulate cancer cell migration." (PMID 24512624, 2014). "In addition, strong positive staining for CD44 was observed not only on the surface of salivary gland appearing structure, but also on the carcinoma cells within the tumor mass." (PMID 24612587, 2014).
tumor (continued). "Specifically, we were interested in determining whether the CD271+ cells possessed the primary tumor initiating capacity among the CD44+ population and if the CD44+CD271+ cells represented the more specific TIC population in SCCHN." (PMID 25149537, 2014). "The expression of CD44 and its relationship with tumor prognosis remains controversial." (PMID 24699672, 2014). "It has also been demonstrated that cancer cells that undergo through epithelial to mesenchymal transition (EMT) acquire a basal CD44+/CD24low/− cancer stem-like phenotype with increased capacity for self-renewal, invasion, drug resistance, and tumor progression." (PMID 24816249, 2014). "Finally, authors demonstrated that TGF-β treated cells displayed a greater capacity of tumor-sphere formation, which were also enriched in CD44 and SOX2." (PMID 24527460, 2014). "CD44 protein is also a direct target of the tumor-suppressor miR-708." (PMID 25309903, 2014). "Although CD44 plays an important role in many cell processes, including growth, differentiation and motility, there are discrepancies in the literature about the roles of CD44v and CD44s in tumor progression." (PMID 24708709, 2014). "In addition, our results are similar to earlier reported studies which found CD44 to be abundantly expressed in tumor cells of HNSCC." (PMID 24533098, 2014). "We hypothesized that if MSCs were involved in tumor recurrence and metastasis to the lung from the primary tumor, a Sca-1+-CD44+ population of cells should be present in the primary tumors." (PMID 24581230, 2014). "Its main receptor is CD44 which is present at the surface of various normal or tumor cells." (PMID 24739440, 2014). "However, we observed a difference in CD44 expression when we stratified the patients according to tumor lymph node invasion with the data showing a decrease of CD44 expression in CRC in sequence from N0 to N2." (PMID 24864242, 2014). "Both CD44 and HA are overexpressed/elevated at sites of tumor attachment." (PMID 24606718, 2014). "CD44 proteins have been studied in relation to tumor malignancy and metastatic potential." (PMID 25112408, 2014). "In addition to its well-known biocompatibility, hyaluronan was chosen because of its capability to selectively target tumor cells through the binding to CD44." (PMID 25383653, 2014). "Another explanation could be that HA-CMC barrier HA shows less affinity for CD44-expressing tumor cells." (PMID 24739440, 2014). "The luciferase activity normalized to that of firefly was significantly reduced in the tumor cells stably transfected with miR-34a precursor, and the effect was abolished by mutating the putative miR-34a–binding site within the 3’-UTR of CD44." (PMID 25551284, 2014). "Paradoxically, however, CD44 has been described as a tumour suppressor in some other cancers." (PMID 24512624, 2014). "CD44, which is a type I transmembrane glycoprotein that serves as the receptor for the extracellular matrix component, hyaluronic acid, was one of the first markers of solid tumors that was shown to be enriched in tumor-initiating cells." (PMID 23229446, 2013). "Merlin, known to have tumor suppressor activity upon binding to the cytoplasmic domain of HA-interacting CD44 and thereby conferring cell growth arrest by contact inhibition, was considered as a candidate molecule contributing to the regulation of 143-B cell aggressiveness." (PMID 23565227, 2013). "The majority of the tumours from the TP53INP1, LATS2 and CD44 silencing group were poorly differentiated, and the tumour area percentage were more than 80%, while most of the tumours from the MIA-V control group were well differentiated, and the tumour area percentage were less than 20%." (PMID 23857777, 2013). "However, increased percentages of total CD44+ T cells observed in the TDLN compared with NDLN (d.n.s) suggest that tumor specific responses were occurring." (PMID 23554861, 2013).